B3GNT5 (UDP-GlcNAc:betaGal beta-1,3-N-acetylglucosaminyltransferase 5)
Diseases named in the same sentence as B3GNT5 in open-access papers (continued):
Sharing a sentence is not in itself a finding about the gene and the disease.
cancer (7 papers, 2017 to 2024). A tumor composed of atypical neoplastic, often pleomorphic cells that invade other tissues. "The most common changes across various cancer types were amplifications of B3GNT5 gene, followed by mutations and deep deletions." (PMID 39671359, 2024). "Furthermore, our results indicated a close association between B3GNT5 expression and immune checkpoints across various cancer types in the TCGA database." (PMID 39671359, 2024). "We conducted a thorough analysis on alterations in pan-cancers, encompassing a total number of 10,953 patients, to identify potential genetic modifications of B3GNT5 that could be linked to tumorigenesis." (PMID 39671359, 2024). "Hence, the aberrant B3GNT5 expression observed in cancer cells may be closely linked to cancer progression and prognosis." (PMID 39671359, 2024). "We analyzed the expression levels of B3GNT5 among various cancer types using GTEx database data as controls." (PMID 39671359, 2024). "In this research, we performed an initial assessment of B3GNT5 expression and its prognostic relevance across multiple cancer types, revealing high expression levels to be present in 18 of these tumors." (PMID 39671359, 2024). "B3GNT5 expressional abundance in multiple cancer forms establishes its oncogenic significance, with ESCA, LUSC and HNSC demonstrating the highest expression levels." (PMID 39671359, 2024). "Our research utilized the Pan-Cancer dataset from The Cancer Genome Atlas (TCGA) to explore the functional role of B3GNT5." (PMID 39671359, 2024). "Additional experiments are necessary to evaluate the mechanisms by which B3GNT5-mediated interactions of cancer stem cells (CSCs) with immune cells, as well as to validate the potential of B3GNT5 as an immune checkpoint target in clinical trials." (PMID 39671359, 2024). "Nevertheless, the biological function of B3GNT5-mediated GSLs is rather limited in the context of cancer and remains to be explained." (PMID 28358117, 2017). "In this study, we successfully created a site-specific and heritable B3GNT5 knockout in human cancer cell lines." (PMID 28358117, 2017). "In this research, we explored the expression of B3GNT5 and its correlation with cancer prognosis by utilizing data from The Cancer Genome Atlas (TCGA), Genotype-Tissue Expression (GTEx), and Cancer Cell Line Encyclopedia (CCLE) databases obtained through the UCSC XENA database." (PMID 39671359, 2024). "It is evident that the successful B3GNT5 deletion performed in this study may be further applied to investigate the lectin binding specificities (e.g. Shiga toxin) in other human cancer cell lines expressing Gb3, nLc4 and P1." (PMID 28358117, 2017). "In contrast to this ambiguity, the GlycoEnzOnto ontology suggests that the impact of cancer is likely to be more severe on lactosylceramide biosynthesis initiating enzymes: A4GALT5, B3GALT5, B3GNT5 and B4GALT6." (PMID 36282863, 2022). "Knockout of B3GNT5 strongly reduced surface expression of SSEA-1 and impeded cancer stem cell (CSC)-like properties of BLBC cells." (PMID 35526049, 2022). "It is envisioned that this gene-editing technology will serve as a useful platform to facilitate the downstream investigation of B3GNT5 and its regulation of both GSL and protein glycosylation in cancer development and progression." (PMID 28358117, 2017). "Through our analysis of various stages of cancer defined by the World Health Organization (WHO) and B3GNT5, we discovered that the higher the stage in KICH, LIHC, LUAD, PAAD, THCA, and UCEC, the greater the expression of B3GNT5." (PMID 39671359, 2024). "In various cancer cell lines, the expression of B3GNT5 was evaluated, revealing that the HNSC, ESCA, small cell lung cancer (SCLC), and PAAD cell lines exhibited the highest levels of B3GNT5 expression." (PMID 39671359, 2024).
B3GNT5 also shares sentences with these, for which no sentence is quoted: ovarian carcinoma (4 papers); lung carcinoma (2); alopecia (1); autism (1); gastric carcinoma (1); glaucoma (1); ischemic stroke (1); pancreatic adenocarcinoma (1); prostate adenocarcinoma (1); skin cutaneous melanoma (1); testicular germ cell tumor (1); thyroid carcinoma (1).